SOX2 (SRY-box transcription factor 2)
Diseases named in the same sentence as SOX2 in open-access papers (continued):
Sharing a sentence is not in itself a finding about the gene and the disease.
esophageal squamous cell carcinoma (continued). "In esophageal squamous cell carcinoma (ESCC), SOX2 binds to the MIAT promoter region to promote MIAT expression." (PMID 35070996, 2021). "The TP63/SOX2/CCAT1 complex activates EGFR, which activates its downstream signaling pathways in esophageal SCC." (PMID 32164712, 2020). "For example, the transcription factors, tumor protein p63 (TP63) and SRY-box transcription factor 2 (SOX2), which co-bind to the promoter and super-enhancer regions of the lncRNA CCAT1, regulate lineage-specific expression patterns in esophageal SCC." (PMID 32164712, 2020). "A high level of SOX2 protein expression and elevated gene copy numbers have been reported in SCLC and in lung and esophageal SCCs, which indicate that SOX2 is an important oncogene and confirms its identity as a genuine SCLC driver gene." (PMID 32130794, 2020). "Splice variants (SOX2OT‐S1 and SOX2OT‐S2) have been identified to co‐upregulate with SOX2 and OCT4 (two key regulators of pluripotency) in esophageal squamous cell carcinoma." (PMID 29504701, 2018). "A clustered abnormality in copy number was observed in several genes, including CCND1 and SOX2 and/or TP63, in esophageal SCC, whereas a more widespread genomic instability and total DNA copy number alterations were observed in esophageal ADC." (PMID 33748520, 2018). "Here we report a novel SOX2-targeting therapy using an ATF for the treatment of lung and esophageal SCC." (PMID 29262545, 2017). "In order to target SOX2 as a candidate oncogene of lung SCC and esophageal SCC, we have developed a zinc finger-based artificial transcription factor (ATF) to selectively suppress SOX2 expression in cancer cells." (PMID 29262545, 2017). "We showed that ATF/SOX2 up-regulated CDKN1A, one of the target genes of SOX2, and induced cell G1 cycle arrest more effectively than shSOX2 in SOX2-expressing EBC2 lung cells and TE4 esophageal SCC cells." (PMID 29262545, 2017). "Ad-ATF/SOX2 up-regulated CDKN1A mRNA and protein expression more significantly than did Ad-shSOX2 in SOX2-expressing lung and esophageal SCC cells in vitro." (PMID 29262545, 2017). "Both Ad-shSOX2 and Ad-ATF/SOX2 effectively suppressed SOX2 expression in EBC2 lung SCC cells, TE1 and TE4 esophageal SCC cells 48 hours after adenoviral infections." (PMID 29262545, 2017). "As we have previously reported, SOX2OT is spliced into several transcript variants, including SOX2OT, SOX2OT-S1, and SOX2OT-S2 which co-upregulated with master regulators of pluripotency, SOX2 and OCT4, in esophageal squamous cell carcinoma (ESCC)." (PMID 26136768, 2015). "Like OCT4B1, SOX2 is reported to act as an oncogene, being upregulated in CRC, and in esophageal squamous cell carcinoma, where it correlated to poor clinical outcome." (PMID 25340937, 2014). "SOX2 has a well-characterized, prooncogenic effect in esophageal squamous cell carcinomas, but there is a lack of in vivo models elucidating the role of SOX2 in the adult foregut epithelium and its possible role in metaplasia of that epithelium." (PMID 40587339, 2025). "Similarly, the expression of B7-H4 correlated with stemness-related markers (i.e., CD44, SOX-2, SOX-9, OCT4) in NSCLC and esophageal squamous cell carcinoma (ESCC)." (PMID 41233805, 2025). "Ad-ATF/SOX2 induced CDKN1A expression in all three kinds of SOX2-expressing lung and esophageal SCC cells but not in all five kinds of SOX2 negative cells." (PMID 29262545, 2017). "Whether SOX2 and ACTL6A/TP63 interact with the Hippo‐YAP1 pathway in esophageal squamous cell carcinoma (ESCC) remains unclear." (PMID 31560173, 2019). "On the other hand, the PI3 Kinase inhibitor wortmannin suppressed SOX2 expression in EBC2 lung SCC cells and in TE1, TE10 esophageal SCC cells whereas ATF/SOX2 did not alter phosphorylated AKT (pAKT) expression, suggesting that pAKT might be an upstream regulator of SOX2 in these kinds of cells." (PMID 29262545, 2017).
esophageal squamous cell carcinoma (continued). "In addition, the ATF more significantly suppressed cell viability and colony formation of SOX2-expressing lung and esophageal SCC cells compared to shSOX2, whereas little CDKN1A expression was induced after Ad-ATF/SOX2 infection in SOX2 negative lung SCC cells and normal human cells HUVEC and NHLF." (PMID 29262545, 2017).
hepatocellular carcinoma (65 papers, 2012 to 2026). A malignant tumor that arises from hepatocytes. "The expression of SOX2 is positively associated with the aggressive of hepatocellular carcinoma and functions as an independent prognostic marker for this malignancy." (PMID 39976818, 2025). "Studies have demonstrated that SOX2 not only facilitates the EMT in hepatocellular carcinoma cells, but is also correlated with poor survival outcomes and metastasis in patients diagnosed with hepatocellular carcinoma." (PMID 39976818, 2025). "miR-2117, functioning as a tumor suppressor, inhibits the self-renewal of CSCs by directly repressing the transcription factor SOX2 in sorted EpCAM+ or CD24+ primary hepatocellular carcinoma (HCC) cells." (PMID 40710326, 2025). "O-GlcNAcylatd eIF4E directly interacted with 5′UTR of SOX2 to result in an enrichment of CD133+ hepatoma cells." (PMID 37298124, 2023). "The MUC15/c-Met/PI3K/AKT/SOX2 axis determines the responses of hepatoma cells to lenvatinib treatment, as supported by the observation that MUC15 overexpression abrogates lenvatinib resistance." (PMID 36980210, 2023). "More importantly, our data demonstrated that SOX2 is required for MUC15-mediated lenvatinib response in hepatoma cells." (PMID 35236826, 2022). "Other stemness-related markers, such as CD133, NANOG, and SOX2, are upregulated in hepatocellular carcinoma cell lines HepG2 and HCC-LM3, overexpressing AP4." (PMID 33567514, 2021). "Furthermore, elevated expressions of RAGE, thyroid transcription factor 1 (TTF-1), glucose transporter 1 (GLUT-1), and SOX2 were suggested to be early events during the development of HCV (hepatitis C virus) associated hepatocellular carcinoma (HCC)." (PMID 34199060, 2021). "Down-regulation of NANOG in human hepatocellular carcinoma decreases the expression of SOX2, OCT4, and KLF4, giving rise to the reduced proliferation, invasion, and migration of cancer cells[34 ▶]." (PMID 32429647, 2020). "Transfection of SOX2 into hepatocellular carcinoma cells results in the expression of CD133 and OST3 stem cell markers and mammosphere formation." (PMID 32523653, 2020). "SOX2 activates the expression of programmed death ligand-1 (PD-L1) through direct binding to the PD-L1 promoter in hepatoma cells." (PMID 32121397, 2020). "OGT activated stem‐like cell potential in hepatoma through eukaryotic initiation factor 4E (eIF4E) which bound to stem‐related gene Sox2 5'‐untranslated region." (PMID 30677218, 2019). "Separate studies have reported that expression of SOX2 and SOX2OT in hepatocellular carcinoma is each associated with poor prognosis." (PMID 28388544, 2017). "For example, CD24+ hepatocellular carcinoma cells showed an increased propensity for self-renewal, differentiation and metastasis as well as enriched levels of Sox2 and Oct4 expression." (PMID 26076835, 2015). "In hepatocellular carcinoma, Sox2 and Oct4 were identified as independent prognostic factors with poorest prognosis in patients with tumours that co-expressed Sox2/Oct4 proteins." (PMID 22433967, 2012). "Furthermore, in hepatocellular carcinoma models, higher nuclear C7 expression upregulates stemness-associated genes (OCT4, SOX2, and MYC) through LSF-1 activation." (PMID 40806542, 2025). "In addition, studies on hepatocellular carcinoma have shown that Sox2 can directly bind to the promoter region of PD-L1 and activate its expression, which, the authors of one study suggest, leads to tumor-cell proliferation." (PMID 36975539, 2023). "Furthermore, western blot analysis showed that MUC15 was downregulated and c-MET, p-AKT was upregulated in SOX2 knockdown hepatoma spheroids." (PMID 35236826, 2022). "Importantly, MUC15/c-MET/PI3K/AKT/SOX2 axis determines the responses of hepatoma cells to lenvatinib treatment, and MUC15 overexpression abrogated lenvatinib resistance." (PMID 35236826, 2022). "Notably, western blot analysis found that SOX2 was also downregulated in MUC15 overexpression hepatoma spheroids." (PMID 35236826, 2022).
hepatocellular carcinoma (continued). "HBV activates SOX2 expression in human hepatoma cells and SOX2, in turn, represses HBV replication." (PMID 32121397, 2020). "Moreover, the downregulation of Mcl-1 and Sox2 by ψ-Bufarenogin was markedly attenuated in hepatoma cells that were transfected with a dominant negative mutant of Akt, suggesting that Akt was involved in a ψ-Bufarenogin-mediated reduction of Mcl-1 and Sox2." (PMID 25890498, 2015). "Moreover, ψ-Bufarenogin decreased the number of hepatoma stem cells through Sox2 depression and exhibited synergistic effect with conventional chemotherapeutics." (PMID 25890498, 2015). "Embryonic stem cell transcription factors, such as Nanog and sex determining region Y-Box Transcription Factor 2 (SOX2), have been shown to help maintain hepatocellular carcinoma (HCC) and oligodendroglioma CSC self-renewal." (PMID 35053542, 2022). "In hepatocellular carcinoma (HCC), ascorbate was shown to be preferentially active against cancer cells with a stem-cell like phenotype (Sox-2, Oct-4, Lin28, or CD133 positive) in comparison to the cancer-stem cell marker negative liver cancer cells." (PMID 35406796, 2022). "In this study, we determined the involvement of SOX2 and its downstream signaling molecules in hepatocellular carcinoma (HCC) progression." (PMID 33952719, 2021). "In a previous study, it was revealed that HBV could induce the production of cancer stem cells (CSCs)-related markers (CD133, CD117, and CD90) and CSCs-related genes (Klf4, SOX2, Nanog, c-Myc, and Oct4) and facilitate the self-renewal of CSCs in human hepatoma cells." (PMID 32121397, 2020). "Interestingly, in hepatocellular carcinoma, SOX2 induces the expression of SLUG47." (PMID 23982413, 2013). "MUC15 inhibits hepatoma cell self-renewal, malignant proliferation, tumorigenicity, and chemoresistance by interacting with c-Met and subsequently inactivating the PI3K/AKT/SOX2 signaling pathway." (PMID 36980210, 2023). "Cancer cells exhibit the ability to prevent ferroptosis by expressing high levels of SLC7A11, which is regulated by NRF2, SOX2 in lung cancer stem-like cells, and YAP/TAZ pathway in hepatocellular carcinoma (HCC) leading to ferroptosis resistance." (PMID 36289191, 2022). "Under increased substrate stiffness, hepatocellular carcinoma cells (HCC) demonstrate enhanced features of stemness and upregulation of Akt, mTOR, 4E-BP, and SRY (sex-determining region Y)-box 2 (SOX2) phosphorylation." (PMID 35163745, 2022). "In present study, we revealed that MUC15 downregulated SOX2 to inhibits T-ICs generation and weaken TIC-like properties of hepatoma cells, thus suppressing the initiation and progression of liver cancer." (PMID 35236826, 2022). "On the contrary, HLF overexpression was found to promote the evolution of sorafenib resistance in patients with hepatocellular carcinomas via upregulation of OCT4 and SOX2." (PMID 35205284, 2022). "Conversely, SOX2 overexpression decreased the level of MUC15 and increased the levels of c-MET, p-AKT in hepatoma spheroids, which further clarify that the MUC15/c-MET/PI3K/AKT/SOX2/miR-183-5p.1 regulatory circuit in liver T-ICs." (PMID 35236826, 2022). "More importantly, introduction of SOX2, AKT or c-MET alleviated lenvatinib sensitivity in MUC15 overexpression hepatoma cells." (PMID 35236826, 2022). "COL1A1 confers a survival advantage and enhanced Hepatocellular Carcinoma (HCC) cell clonogenicity, tumorsphere formation and expression of stemness genes like SOX2, OCT4 and CD133." (PMID 33096662, 2020). "Bcl-3 has been shown to be important for Sox2 expression in murine embryonal stem cells and AKT was found to drive Sox2 expression in hepatocellular carcinoma cells." (PMID 33228022, 2020). "MiR-126 represses proliferation and triggers cell death in hepatocellular carcinoma (HCC), at least in part, by acting on Sox2." (PMID 32554852, 2020).
hepatocellular carcinoma (continued). "In hepatocellular carcinoma, miR-486-5p diminishes Sirt1 expression by binding to its 3′UTR, thereby inhibiting the expression of stem cell-related genes (e.g., SOX2, OCT4, and CD13) and ultimately suppressing the self-renewal capacity of hepatocellular carcinoma cancer stem cells (CSCs)." (PMID 40710326, 2025). "Additionally, stemness genes, such as Nanog, Sox2, and Oct4, were expressed in EpCAM-positive HCC cells and TSC2-AKT signaling activated upon Sorafenib treatment, further exacerbating hepatocellular carcinoma progression." (PMID 32466488, 2020). "SOX2 and SOX2OT are also likely to be co-expressed in hepatocellular carcinoma." (PMID 28388544, 2017). "A synergistic action of Sox2 and TAZ has been reported in hepatocellular carcinoma (HCC) not only to promote cell proliferation but also to promote the epithelial-to-mesenchymal transition (EMT) for the initiation of metastatic invasion." (PMID 36833308, 2023). "In hepatocellular carcinoma (HCC), downregulation of CHEK1 by silencing LINC01224 or elevating miR-330-5p could inhibit stemness, by reducing the expression of CSC biomarkers (OCT4, CD133 and SOX2)." (PMID 32121037, 2020). "However, a previous report indicated that while NANOG bound to the ICAM1 promoter region in CIC-like hepatocellular carcinoma cells, OCT4 and SOX2 did not." (PMID 31619256, 2019).
bladder cancer (64 papers, 2012 to 2025). "In bladder cancer, tumor progression is associated with the strong up-regulation of SOX2 and NANOG and the consequent acquisition of cancer stem cell properties." (PMID 38096163, 2023). "Currently, SOX2 is thought to be a cancer stem cell marker in relation to bladder tumors and Sox2 knockout within primary invasive bladder cancer caused enhanced tumor regression." (PMID 32427884, 2020). "Box-and-whisker plots showed that SOX2 expression was also associated with advanced tumor grade of bladder cancer." (PMID 32427884, 2020). "Here, we observed that SOX4 is mainly amplified in primary bladder tumors, whereas only SOX2 expression is associated with poor recurrence-free survival in patients with bladder cancer." (PMID 32427884, 2020). "The tumors harboring high-SOX2/high-IGF1R signature are associated with the worst survival outcome in bladder cancer patients." (PMID 32427884, 2020). "In conclusion, we found a significant association between SOX2 and livin expressions in primary bladder cancers." (PMID 28983346, 2015). "Therefore, Sox2 serves not only as a diagnostic marker but also as a prognostic factor for bladder cancer progression." (PMID 40635786, 2025). "SOX2 also regulates pluripotency, maintains stem cell-like characteristics, and has been associated with poor survival in multiple cancers, including bladder cancer." (PMID 39337385, 2024). "Moreover, we found that SOX2 expression is associated with poor pathological differentiation, emphasizing its involvement in bladder cancer malignancy." (PMID 32427884, 2020). "Sox2+ cells isolated from bladder cancer tissues demonstrate a greater ability to regenerate tumors compared to Sox2-cells." (PMID 40635786, 2025). "While Sox2 is minimally expressed in normal bladder epithelium, its expression is significantly elevated in bladder cancer." (PMID 40635786, 2025). "And our findings combined with others’ have revealed that SOX2 is a key regulator of bladder cancer’s invasion and lineage marker expression." (PMID 41145440, 2025). "Specifically, we found that YTHDC2 can regulate the characteristics of bladder cancer stem cells by recognizing m6A-modified SOX2." (PMID 41145440, 2025). "Mechanistically, YTHDC2 inhibits bladder cancer progression by binding to m6A-modified SOX2 mRNA and suppressing SOX2 protein translation." (PMID 41145440, 2025). "In our study, YTHDC2 modulated SOX2 at translational level in bladder cancer cells, consistent with the established mechanism observed for this m6A reader across multiple cancer types." (PMID 41145440, 2025). "In N-butyl-N-(4-hydroxybutyl) nitrosamine (BBN)-induced murine bladder cancer model, a subpopulation of bladder cancer cells with high SOX2 levels displays stem cell-like features, including self-renewal and enhanced lineage plasticity." (PMID 41145440, 2025). "In conclusion, our study identifies YTHDC2 as a tumor suppressor in bladder cancer through inhibiting SOX2-mediated cell pluripotency and underscores the therapeutic potential of targeting the YTHDC2-SOX2 axis in bladder cancer." (PMID 41145440, 2025). "An inverse correlation was found between E-cadherin and NANOG/SOX2 expression in bladder cancer tissues." (PMID 37627900, 2023). "SOX2OT positively regulates SOX2 transcription by sponging miR-200c and endorses stemness in bladder cancer and pancreatic ductal adenocarcinoma cells." (PMID 37149646, 2023). "One compound ChlA-F blocked cell invasion via inhibition of SOX2 protein by USP8-mediated SOX2 degradation in bladder cancer." (PMID 37215134, 2023). "Another study revealed that USP8 can regulate SOX2 ubiquitination and degradation in bladder cancer." (PMID 37215134, 2023). "HnRNP K can also bind to the promoter of SOX2 mRNA and promote its translation, thereby promoting the proliferation and spheroid-forming ability of bladder cancer cells." (PMID 36831493, 2023).